RIMS1 (regulating synaptic membrane exocytosis 1)
Description:
Rab effector involved in exocytosis (By similarity). May act as scaffold protein that regulates neurotransmitter release at the active zone. Essential for maintaining normal probability of neurotransmitter release and for regulating release during short-term synaptic plasticity (By similarity). Plays a role in dendrite formation by melanocytes.
Synonyms: KIAA0340; RAB3IP2; RIM1; RIM; CORD7
Tractability: Antibody: UniProt places it where antibodies can reach, with medium confidence; its Gene Ontology location is reachable by antibodies, with medium confidence. PROTAC: ubiquitination databases record sites on it; its protein half-life has been measured.
Gene: Protein-coding gene on chromosome 6 (71,886,550 to 72,403,150, forward strand). Ensembl gene ENSG00000079841.
Subcellular location: Cell membrane; Synapse; Presynaptic cell membrane
Pathways (Reactome):
Neuronal System: Acetylcholine Neurotransmitter Release Cycle; Dopamine Neurotransmitter Release Cycle; GABA synthesis, release, reuptake and degradation; Glutamate Neurotransmitter Release Cycle; Norepinephrine Neurotransmitter Release Cycle; Serotonin Neurotransmitter Release Cycle
Gene Ontology:
Molecular function: protein binding; RNA binding; GTPase regulator activity; small GTPase binding; structural constituent of presynaptic active zone
Biological process: acrosomal vesicle exocytosis; positive regulation of dendrite extension; protein-containing complex assembly; calcium-ion regulated exocytosis; membrane fusion; positive regulation of excitatory postsynaptic potential; positive regulation of gene expression; positive regulation of inhibitory postsynaptic potential; regulated exocytosis; regulation of neurotransmitter secretion; regulation of synaptic vesicle exocytosis; secretion; synaptic vesicle exocytosis; synaptic vesicle priming; exocytosis; intracellular protein transport; maintenance of presynaptic active zone structure
Cellular component: cytosol; plasma membrane; presynaptic active zone; presynaptic active zone cytoplasmic component; presynaptic membrane; membrane; synapse
Genetic constraint (gnomAD): Loss-of-function variants: 37 observed, 98.07 expected, observed/expected ratio (o/e) 0.38, 90% interval 0.29 to 0.5. The upper end of that interval is the gene's LOEUF score, 0.5, which puts it in group 2 of 6, group 1 being the genes least tolerant of losing a copy. Missense variants: 1,463 observed, 1,462.5 expected, observed/expected ratio (o/e) 1, 90% interval 0.96 to 1.04. Synonymous variants: 611 observed, 552.55 expected, observed/expected ratio (o/e) 1.11, 90% interval 1.03 to 1.18.
Homologues: Orthologues: chimpanzee RIMS1 (100% identical), macaque RIMS1 (99% identical), pig RIMS1 (94% identical), dog RIMS1 (91% identical), rat Rims1 (90% identical), mouse Rims1 (90% identical), tropical clawed frog rims1 (76% identical), zebrafish rims1a (58% identical), rabbit RIMS1 (58% identical), Drosophila melanogaster Rim (31% identical), Caenorhabditis elegans unc-10 (26% identical), guinea pig Rims1 (13% identical). Paralogues in human: RIMS2 (56% identical), RIMS3 (12% identical), RIMS4 (10% identical), NANOGNB (3% identical).
Diseases named in the same sentence as RIMS1 in open-access papers:
RIMS1 is named in the same sentence as 46 diseases in open-access papers, as found by Europe PMC text mining. Sharing a sentence is not in itself a finding about the gene and the disease. The quoted sentences say what the papers report.
schizophrenia (6 papers, 2014 to 2024). A major psychotic disorder characterized by abnormalities in the perception or expression of reality. "However, several RIM proteins that are necessary for VGCCs regulation, including the schizophrenia-associated RIMS1 (Schizophrenia Working Group of the Psychiatric Genomics, 2014), are detected in the p140Cap interactome." (PMID 28713243, 2017). "These included schizophrenia candidate genes (GRIA1, RIMS1, DLGAP2, GRIN2A, and NRXN1) and several interaction partners." (PMID 25484875, 2014).
autism (5 papers, 2018 to 2023). Persistent deficits in social interaction and communication and interaction as well as a markedly restricted repertoire of activity and interest as well as repetitive patterns of behavior. "Genes located in proximal 6q that have been linked to autism are RIMS1 (regulating synaptic membrane exocytosis 1, MIM*606629), PHIP, SYNCRIP and ZNF292 (zinc finger protein 292, MIM*616213)." (PMID 29904178, 2018). "RIMS1 has previously been found to have altered gene expression in cortical brain samples from SCZ and autism patients." (PMID 37488168, 2023).
Retinal dystrophy (3 papers, 2022 to 2025). Retinal dystrophy is an abnormality of the retina associated with a hereditary process. "Clear evidence of association between RIMS1 and a retinal dystrophy is yet to be described." (PMID 35947379, 2022). "Of these patients, seven had monoallelic pathogenic variants in ABCA4, one had biallelic variants of uncertain significance (VUS) in ABCA4, two had monoallelic VUS in ABCA4, and eight harbored VUS in other retinal dystrophy-related genes, including KCNV2, RIMS1, CRB1, CFH, RP1L1, UNC119, and SEMA4A." (PMID 41234456, 2025).
Alzheimer disease (2 papers, 2018 to 2022). A progressive, neurodegenerative disease characterized by loss of function and death of nerve cells in several areas of the brain leading to loss of cognitive function such as memory and language. "In the AppNL-F knockin mouse model of Alzheimer’s disease, increased turnover resulted from imbalances in both synthesis and degradation, converging on proteins associated with synaptic vesicle recycling (Dnm1, Cltc, Rims1) and mitochondria (Fis1, Ndufv1)." (PMID 34979241, 2022).
bipolar disorder (2 papers, 2019 to 2024). A disorder of the brain that causes unusual shifts in mood, energy, activity levels and the ability to carry out day-to-day tasks. "Moreover, Rbfox1, one of the plasticity genes identified in the enrichment analyses is also linked to risk for ASDs, TRANK1 is a susceptibility gene for bipolar disorder, and RIMS1 was identified in a PTSD TWAS." (PMID 38263132, 2024).
gastric cancer (2 papers, 2023 to 2024). A primary or metastatic malignant neoplasm involving the stomach. "RIMS1 mutations impacted survival in patients with pancreatic cancer and gastric cancer." (PMID 39518157, 2024). "However, RIMS1, another member of the RAS gene superfamily with similar structure and function to RIMS2, has shown a promising prognostic value in several kinds of cancer, like gastric cancer." (PMID 37020199, 2023).
glioma (2 papers, 2021 to 2023). A benign or malignant brain and spinal cord tumor that arises from glial cells (astrocytes, oligodendrocytes, ependymal cells).
Macular dystrophy (2 papers, 2022 to 2023). Macular dystrophy is a nonspecific term for retinal degeneration, generally confined to the macula, usually presumed of genetic origin. "In this report of four patients with macular dystrophy and history suggestingStargardt-like disease, two patient’s phenotypes were related to AD genes(RIMS1 and CRX) and those of the other twopatients were related to AR genes (CRB1 andRDH12)." (PMID 36995812, 2023). "In contrast to the RIMS1 variant, the PROM1 variant is highly enriched in patients with macular dystrophy and CORD9 and submitted 16 times to ClinVar (15 pathogenic and 1 likely pathogenic, accessed March 2021)." (PMID 35947379, 2022). "We report the findings of macular dystrophy in one family member thought previously to be unaffected in the absence of the RIMS1 variant, providing the first evidence of non-segregation of RIMS1 with disease in the family." (PMID 35947379, 2022). "One family member, now known to have macular dystrophy, was previously reported not to harbor the RIMS1 p.Arg820His variant, but was unavailable for PROM1 testing (IV:9)." (PMID 35947379, 2022). "One affected family member is now known to have macular dystrophy in the absence of RIMS1 p.Arg820His." (PMID 35947379, 2022).
angioedema (1 paper, 2025). Swelling involving the deep dermis, subcutaneous, or submucosal tissues, representing localized edema. "We also found SNPs located close to the genes PRKCQ (protein kinase C theta), RAD51B (RAD51 Paralog B), and RIMS1 (regulating synaptic membrane exocytosis 1), which have previously been linked with drug-induced angioedema." (PMID 41189626, 2025).
autism spectrum disorder (1 paper, 2018). A spectrum of developmental disorders that includes autism, and Asperger syndrome. "However, others have shown an increased number of truncating RIMS1 variants in individuals with autism spectrum disorder." (PMID 29904178, 2018). "Remarkably, we observed an autism spectrum disorder in 7/13 individuals with an HTR1E and a SYNCRIP deletion, while the numbers were 3/13 for RIMS1, 3/12 for HTR1B, 3/14 for PHIP and 4/10 for ZNF929." (PMID 29904178, 2018).
breast carcinoma (1 paper, 2025). "However, direct evidence linking RIMS1, IK, SF3B1, and CBR1 genes specifically to lactylation modifications in breast cancer is lacking." (PMID 40406140, 2025).
cataract (1 paper, 2016). Partial or complete opacity of the crystalline lens of one or both eyes that decreases visual acuity and eventually results in blindness. "Patient 8 had bilateral retinal detachment and cataracts, which were not mentioned in those reported patients with RIMS1 mutations but can be associated with RP." (PMID 27788217, 2016).
cervical cancer (1 paper, 2025). A primary or metastatic malignant neoplasm involving the cervix. "According to our findings, the CHD6 gene exhibited higher expression than the RIMS1, MORC4, FMO5, TIAM1, and other genes in cervical cancer." (PMID 40847033, 2025).
congenital nystagmus (1 paper, 2020). Nystagmus present at birth or caused by lesions sustained in utero or at the time of birth. "Additionally, SLC38A8 contributes to congenital nystagmus, and RIMS1 and CABP4 are associated with dystrophy and synaptic disorder of cone-rod, respectively." (PMID 33330132, 2020).
craniopharyngioma (1 paper, 2021). A benign, partly cystic, epithelial tumor of the sellar region, presumably derived from Rathke pouch epithelium. "Furthermore, POP4, a GNG5 coexpressing promoter gene, is highly expressed in prostate cancer cells, while RIMS1, a GNG5 coexpressing suppressor gene, is lowly expressed in craniopharyngioma." (PMID 34098960, 2021).
Dravet syndrome (1 paper, 2020). "It should also be noted that besides these well-characterized syndromic genes, another patient carrying the RIMS1 splice variant received a diagnosis of Dravet syndrome but bore no mutation on genes causing this phenotype." (PMID 32094338, 2020).
essential tremor (1 paper, 2021). A relatively common disorder characterized by a fairly specific pattern of tremors which are most prominent in the upper extremities and neck, inducing titubations of the head. "Males with the minor (T) allele at SNP rs12528068 108.6 kb from the RIMS1 gene, which encodes one of four isoforms of presynaptic scaffolding proteins involved in synaptic transmission, have a 2.1-fold increased risk of a history of essential tremor." (PMID 33935957, 2021).
hemangioblastoma (1 paper, 2024). "Recently, mutations in RIMS1 were identified as a potential causal mutation in Chinese familial hemangioblastoma." (PMID 39518157, 2024).
macular coloboma (1 paper, 2022). "Moreover, variations in BEST1 and RIMS1 were reported in a Chinese patient with bilateral macular coloboma." (PMID 36429029, 2022).
mental disorder (1 paper, 2023). A disease that has its basis in the disruption of mental process. "Finally, the mature stage T5 was enriched for synaptic signaling genes (FDR = 5 × 10–16; e.g., CADPS2 and SNAP25) and regulation of membrane potential (FDR = 3 × 10–11; e.g., RIMS1 and SCN2A), and was most specifically marked by RBFOX1, an RNA-binding protein implicated in many mental disorders." (PMID 36865235, 2023).
osteoarthritis (1 paper, 2023). A noninflammatory degenerative joint disease occurring chiefly in older persons, characterized by degeneration of the articular cartilage, hypertrophy of bone at the margins and changes in the synovial membrane. "A GWAS analysis in humans has reported that COX7A2 and RIMS1 were identified as candidate genes for osteoarthritis, and COX7A2 was highly expressed in cartilage." (PMID 36833449, 2023).
ovarian carcinoma (1 paper, 2018). A malignant neoplasm originating from the surface ovarian epithelium. "Analysis of the frequently observed proteins by ANOVA confirmed increases in mean precursor intensity in ZFN91, TRPM5, SIRT1, CHD6, RIMS1, LOC101930455 (XP_005275896), CCDC37 and GIMAP4 between ovarian cancer versus normal female and other diseases or controls by the Tukey–Kramer HSD test." (PMID 30598658, 2018).
retinal disease (1 paper, 2004). "This is illustrated by the finding that the 15K retinome which comprises 15,645 transcripts including those which were solely found in a single study, contains an additional five of the 102 known retinal disease genes (RHOK, MTATP6, CHM, LRAT, RIMS1) not included in the 13K retinome." (PMID 15283859, 2004).
cancer (6 papers, 2018 to 2024). A tumor composed of atypical neoplastic, often pleomorphic cells that invade other tissues. "Integration events occurring in single samples were observed in the following cancer-driver genes: TERT, KMT2B (MLL4), RIMS1, FN1, RBFOX1, CNTNAP2 and THRB7,11,12,14,27,28." (PMID 37400627, 2023).
neurological diseases (3 papers, 2013 to 2019). "So, by combining specific GO term–annotated gene lists and cross-checking with publications, we were able to decrease the number of candidate genes and predict candidate genes (FOXO4, GRM5, RIMS1 and NELL2) for neurological diseases." (PMID 23794737, 2013).
RIMS1 also shares sentences with these, for which no sentence is quoted: tumor (3 papers); infection (2); pancreatic cancer (2); retinitis pigmentosa (2); adenoma (1); alcohol dependence (1); Anxiety (1); cognitive deficits (1); colon cancers (1); colon tumors (1); developmental delay (1); epilepsy (1); generalized epilepsy (1); macular degeneration (1); major depression (1); manic episodes (1); medulloblastoma (1); neuroblastoma (1); prostate carcinoma (1); retinal detachment (1); retinopathy (1).